CD4 (CD4 molecule)
Diseases named in the same sentence as CD4 in open-access papers (continued):
Sharing a sentence is not in itself a finding about the gene and the disease.
vasculopathy (13 papers, 2010 to 2024). "Bm12 mice have a mutation that generates I-ABm12, an altered I-A molecule that is recognized by B6 CD4+ T cells to cause CR-associated fibrosis and vasculopathy within 30 days of HTx." (PMID 39621314, 2024). "Heart allografts transplanted into unmodified Tcrbd−/− recipients remained disease-free (left), confirming that allograft vasculopathy in the reconstituted recipients was mediated by the transferred TCR75 CD4 T cells." (PMID 30728823, 2018). "Using mouse cardiac transplant models, we show that graft-versus-host recognition by passenger donor CD4 T cells markedly augments recipient cellular and humoral alloimmunity, resulting in more severe allograft vasculopathy and early graft failure." (PMID 27134179, 2016). "Adoptive transfer of donor CD4 T cells at time of transplant to recipients of CD4 T cell-depleted bm12.Kd.IE heart allografts restored the development of allograft vasculopathy." (PMID 27134179, 2016). "The marked reduction in the alloimmune response to CD4 T cell-depleted bm12.Kd.IE heart allografts ameliorated graft rejection, in that vasculopathy was minimal in heart allografts from CD4 T cell-depleted donors and comparable to that observed in syngeneic heart transplants." (PMID 27134179, 2016). "Hence, it is unlikely that the donor CD4 T cells survive long enough to contribute directly to the progression of allograft vasculopathy." (PMID 27134179, 2016). "Besides allograft-vasculopathy, we could also show the immigration of immunological relevant cells, such as CD4- and CD68-positive-cells but also their deteriorating effects on muscle tissue." (PMID 32589662, 2020). "From another angle, CD4+ and CD8+ T cells with cytolytic potential present in SSc skin may participate to vasculopathy by enhancing endothelial cell apoptosis." (PMID 34487318, 2023). "Mouse iTreg generated by IFNγ-conditioning of non-regulatory CD4+ T cells in the presence of alloantigen not only prevented the acute rejection of skin and islet allografts, but also the development of chronic allograft dysfunction (CAD)-associated vasculopathy of an arterial transplant." (PMID 22905732, 2012).
benign tumors (11 papers, 2013 to 2025). "The frequency of CD4+ TCM between the benign tumor group and healthy control group was significant (182.34 ± 61.88 vs. 155.69 ± 44.29, p < 0.05)." (PMID 34327142, 2021). "The frequency of CD4+ TSCM in the CRC group significantly differed from the benign tumor group and healthy control group (p < 0.05)." (PMID 34327142, 2021). "In addition, CD4+ TEM significantly differed between the benign tumor group and CRC group [15 (5.4–33.4) vs. 23.4 (13.1–41.5), p < 0.05]." (PMID 34327142, 2021). "In addition, compared with the benign tumor group, the absolute values of CD4+ TN [113.40 (76.66–181.41) vs. 172.99 (119.10–272.97), p = 0.0024] and CD4+ TCM (232.94 ± 112.03 vs. 328.92 ± 152.39, p = 0.0056) were significantly reduced in the CRC group." (PMID 34327142, 2021). "The CD4+ cells correlated with the FOXP3+ cellular infiltrates within the benign tumors." (PMID 29137242, 2017). "Although it is unknown whether macrophages are involved in malignant conversion of benign tumors in ApcMin/+ mice lacking Dok-3, it might be possible that Dok-3–deficient macrophages play a role in the malignant progression by cooperating with CD4+ and CD8+ T cells." (PMID 36970719, 2022). "According to the absolute value of each lymphocyte subgroup, the expression level of CD4+ TSCM in the CRC group was 4.01 (2.32–5.86), which significantly differed from that in the benign tumor group and healthy control group." (PMID 34327142, 2021). "Together, these findings demonstrate that CD4+ and CD8+ T cells, but not B and γδT cells, have an essential role in malignant progression of benign tumors in Apc/Dok3 mice, although the underlying mechanisms are yet unclear." (PMID 36970719, 2022). "However, the absolute values of CD4+ T lymphocyte subsets between the benign tumor group and healthy group were not significantly different." (PMID 34327142, 2021).
connective tissue disease (10 papers, 2005 to 2025). "HLA-DQ2.5-restricted gluten-specific CD4+ T cells of a rare, uniform phenotype are reported in CeD and connective tissue disease." (PMID 39665304, 2025). "Patients with mixed connective tissue disorders also showed increased activation, but with similar engagement of CD4+ and CD8+ T cells." (PMID 20626864, 2010). "A similar pattern was seen among the mixed connective tissue disorder patients, however, with same levels of activation in the CD4+ T cells as in the CD8+ T cells." (PMID 20626864, 2010). "It is unclear if SSc improves during the course of untreated HIV infection similar to the observation in some of the other connective tissue diseases, and if HIV-induced CD4-positive T-lymphocyte loss may account for the low prevalence of some SSc manifestations." (PMID 33447331, 2020). "In our HTLV-1-infected cohort with RA or connective tissue disease, HTLV-1 proviral load correlated positively with the percentage of CD4+ T cells expressing CD45RO and negatively with that of CD4+ T cells expressing CD45RA." (PMID 15686595, 2005). "In healthy donors and connective tissue disease patients 28, virtually all CD146+CD4 T cells are CD45RO+ memory cells, whereas CD146‐negative CD4 cells include both memory and naive populations in proportions that vary between individuals but average approximately 50%." (PMID 25113810, 2015).
head and neck tumors (10 papers, 2014 to 2025). "Genes specifically expressed in T cells (CD4+, regulatory, CD3+, and CD8+), as well as in NK cells and B cells, have been found to be significantly higher in head and neck tumors with active integration." (PMID 38793599, 2024). "Similar results were seen in head and neck tumors, where PTEN HemDel showed higher M0 and M2 macrophages and mast cells and lower CD4 T-cell, CD8+ T-cell, T-regulatory cells, and NK cells." (PMID 36977733, 2023). "To further characterize PD-1hiCD39+ CD4 Tconv TILs, we performed scRNA-Seq of total CD45+ cells isolated ex vivo from 4 head and neck tumors." (PMID 33332284, 2021). "In fact, infiltrations of B cells and CD4 and CD8 T cells are all significantly higher in HPV-positive than in HPV-negative head and neck tumors, suggesting that viral antigens result in an elevated lymphocyte response." (PMID 27549193, 2016). "In this study, we assessed the presence and prognostic value of CD3, CD4, CD8, FoxP3, and PD1 positive TILs, as well as the CD8/FoxP3 ratio, in the head and neck tumor epithelium in pre-treatment biopsies of HNSCC patients using an objective, digital pathology-aided method." (PMID 31980916, 2020).
hematologic cancer (9 papers, 2018 to 2025). "Specifically, less impairment of B cell and CD4+ T cells have been observed in individuals with solid cancers compared to individuals with hematological cancers." (PMID 40873575, 2025). "More specifically, a statistically significant difference was observed in CD4+ T-cells being less frequent in patients with hematologic cancer compared to those who suffer from solid malignancies, whereas CD8+ T-cells were equally detected among those groups." (PMID 37190194, 2023). "Intermediate vaccine responses would be expected for patients with anti-cytotoxic T-lymphocyte antigen-4 therapy, hematologic cancer, and human immunodeficiency virus infection (low CD4 counts)." (PMID 35632555, 2022). "When including only patients with hematologic cancers (n = 8), CD4+ TEM cells were still markedly elevated in T-LGLL." (PMID 35411050, 2022). "Intermediate vaccine responses would be expected for patients with anti-cytotoxic T-lymphocyte antigen-4 therapy, hematologic cancer, and human immunodeficiency virus infection with low CD4 counts." (PMID 35632555, 2022). "In addition, in this second phase, the LymphoclonalTM tube was replaced by LST, which included both CD45 and CD56 for improved distinction between hematopoietic and non-hematopoietic tumors and, e.g., CD4, CD8, anti-Igκλ, and CD38 for more accurate B, T, and NK cell subsetting." (PMID 34638431, 2021). "Flow cytometric analyses of CD4+CD28− T cells confirmed the expected immunophenotype in BM from healthy donors and patients with different hematological cancers, suggesting a robust and efficient prospective isolation of this rare cell type." (PMID 34811546, 2021).
blood cancers (7 papers, 2016 to 2025). "Aberrant transduction of the malignant CD4 T cells might lead to high toxicity and risk of developing a blood cancer as already shown in one case of ex vivo CAR T cell generation." (PMID 39272178, 2024). "Across both solid and blood cancers, immune cell profiles included slightly higher levels of activated NK cells, CD4+ memory cells and CD8+ cells in long overall survival patients, and higher levels of M2 macrophages in short survival patients." (PMID 36649303, 2023). "BPDCN is a CD4+ CD56+ hematologic neoplasm with a propensity for cutaneous involvement." (PMID 40135229, 2025). "However, the integrity of GzmB function in CD4+ T cells may need to be maintained in order to optimize the GVT effect for certain types of blood cancers that are sensitive to GzmB-mediated killing by CD4+ T cells." (PMID 27774524, 2016). "Blastic plasmacytoid dendritic cell neoplasm (BPDCN) is a rare and aggressive hematological neoplasm characterized by CD123+ (IL‐3 receptor) expression and at least one plasmacytoid dendritic cell marker in addition to expression of CD4+ and CD56+." (PMID 38285172, 2024).
colon (7 papers, 2012 to 2023). "Accumulating studies had demonstrated that a large number of CD4+CD25hiCD127low Tregs infiltrate into various types of tumors in humans, including gastrointestinal tract cancer." (PMID 37210494, 2023).
retinopathy (7 papers, 2009 to 2023). "Retinopathy was significantly associated with HAND but HIV-disease factors (CD4, viral load) were not." (PMID 35082308, 2022). "All patients with HIV retinopathy had CD4+ T cell count of <200 cells/μl." (PMID 23710936, 2013). "The majority (71.4%) of participants with HIV retinopathy were categorised at WHO clinical stage 3 or 4, and all had CD4 counts ≤ 150 cells/μL." (PMID 19775470, 2009).
central nervous system disease (5 papers, 2013 to 2023). "Previous studies have found that CD8+ T cells can independently induce mild central nervous system diseases, and CD4+ T cells are the main driving force of CNS autoimmunity." (PMID 35326328, 2022). "The positive influence of CD4+ FoxP3+ regulatory T cells on remyelination was proven in demyelinating central nervous system disorders such as multiple sclerosis." (PMID 29618748, 2018).
CNS tumor (4 papers, 2015 to 2023). "An increased ratio of CCR4+FoxP3+ Tregs to total CD4+ T cells correlates with impairment of CD4+ T cell proliferation in peripheral blood specimens obtained from CNS tumor patients." (PMID 26528477, 2015).
endocrine disorders (4 papers, 2014 to 2024). "All models were adjusted for age, sex, race, (age‐sex, race‐sex interactions), BMI, CD4 cell count, endocrine disorders and concurrent medications that could affect weight." (PMID 33838004, 2021).
genetic disorder (4 papers, 2010 to 2023). "To exclude the possibility that the inhibitory effect was a side effect of a genetic disorder, we treated the CD4+ T cells with PMA/ionomycin to induce RANKL expression." (PMID 28724396, 2017). "Discoveries of genetic diseases that ablate this cellular population have provided insight into their critical functions while transcriptomics, proteomics, and high-resolution microscopy have recently revealed new insights into CD4+ T cell anatomy and physiology." (PMID 37892982, 2023).
musculoskeletal disease (4 papers, 2020 to 2025). "Infiltration of immune cells, including neutrophils, monocytes, and CD4+ T cells, contribute to the pathogenesis of musculoskeletal disease during alphavirus infection in mice." (PMID 32760128, 2020).
gastrointestinal disorders (3 papers, 2014 to 2024). "In the HIV-infected population, administration of probiotics and other specialized nutritional products has led to modest improvements of CD4+ T-cell counts, reduced CD4+ T cell activation, and fewer gastrointestinal disorders." (PMID 25266928, 2014). "HIV associated gastroenteropathy is initiated by early loss of CD4 T cells, loss of mucosal barrier, lack of anti-inflammatory response, increased microbial translocation, and chronic immune activation." (PMID 35281029, 2022).
bone disorder (2 papers, 2013 to 2015). "Therefore, the contraction of the CD28-negative CD4+ T-cell pool that we observed in patients with bone disorders may have resulted from increased activation-induced apoptosis." (PMID 23448662, 2013).
congenital malformations of the nervous system (1 paper, 2026). "Conversely, CD4+CD8+ T cell absolute count, CD25 on IgD+ CD38dim B cell, and CD25 on IgD− CD24− B cell (β values of 0.657, 0.569, and 1.325, respectively, p < 0.05) were positively associated with higher risk of congenital malformations of the nervous system." (PMID 41474150, 2026).
movement disorder (1 paper, 2022). Neurological conditions resulting in abnormal voluntary or involuntary movement, which may impact the speed, fluency, quality and ease of movement. "The number of CD4+ Th cells, CD3+, CD4+, and CD25+ T regulatory cells in 10-month-old mice increased, which was related to movement disorder in mice, and B cells had no significant change." (PMID 36567855, 2022).
neoplastic disorders (1 paper, 2011). "Normal CD4+ lymphocyte counts reduce the chances of suffering from co-infectious and neoplastic disorders." (PMID 21261982, 2011).
neuromuscular disease (1 paper, 2019). "CD45RChigh and CD45RClow/− cells in the CD4+ or CD8+ T cell compartments in the blood of DMD patients were present in comparable proportions to that seen in age-matched individuals hospitalized for pathologies not involving the immune system or neuromuscular diseases." (PMID 31552055, 2019).
CD4 also shares sentences with these, for which no sentence is quoted: viral diseases (26 papers); rubella (14); combined immunodeficiency (13); portal hypertension (11); chronic periodontitis (10); Parkinson’s (9); acute myocardial infarction (8); gastrointestinal disease (7); ventilator-associated pneumonia (7); autoimmune hemolytic anemia (6); hyperuricemia (6); brain disease (5); Hepatosplenomegaly (5); myeloproliferative neoplasm (5); chronic liver failure (4); ependymoma (4); Hypokalemia (4); idiopathic inflammatory myopathy (4); inclusion body myositis (4); left ventricular hypertrophy (4); pericardial tuberculosis (4); rhabdomyosarcoma (4); spinal cord injury (4); tonsillitis (4); acute respiratory failure (3); anal squamous cell carcinoma (3); autoimmune disease of the central nervous system (3); autoimmune pancreatitis (3); cancers of the larynx (3); chronic cervicitis (3).
A further 427 diseases each share a sentence with CD4 in 3 papers or fewer.